BTNL2 (butyrophilin like 2)
Description:
Negative regulator of T-cell proliferation.
Synonyms: BTL-II; HSBLMHC1; BTN7; SS2
Tractability: Antibody: its Gene Ontology location is reachable by antibodies, with high confidence; UniProt predicts a signal peptide or a membrane-spanning region. PROTAC: ubiquitination databases record sites on it.
Gene: Protein-coding gene on chromosome 6 (32,393,339 to 32,407,181, reverse strand). Ensembl gene ENSG00000204290.
Subcellular location: Membrane
Pathways (Reactome):
Immune System: Butyrophilin (BTN) family interactions
Gene Ontology:
Molecular function: signaling receptor binding
Biological process: regulation of cytokine production; T cell receptor signaling pathway
Cellular component: membrane; external side of plasma membrane; plasma membrane
Genetic constraint (gnomAD): Loss-of-function variants: 46 observed, 46.67 expected, observed/expected ratio (o/e) 0.99, 90% interval 0.78 to 1.26. The upper end of that interval is the gene's LOEUF score, 1.26, which puts it in group 5 of 6, group 1 being the genes least tolerant of losing a copy. Missense variants: 461 observed, 618.91 expected, observed/expected ratio (o/e) 0.74, 90% interval 0.69 to 0.8. Synonymous variants: 226 observed, 240.74 expected, observed/expected ratio (o/e) 0.94, 90% interval 0.84 to 1.05.
Homologues: Orthologues: dog BTNL2 (73% identical), pig BTNL2 (72% identical), rat Btnl2 (65% identical), guinea pig BTNL2 (63% identical), mouse Btnl2 (62% identical), chimpanzee BTNL2 (49% identical). Paralogues in human: BTN1A1 (30% identical), BTN2A2 (29% identical), BTN3A3 (28% identical), BTN2A1 (28% identical), BTN3A1 (26% identical), BTNL9 (25% identical), BTN3A2 (21% identical), BTNL3 (21% identical), BTNL8 (20% identical), ERMAP (18% identical), MOG (15% identical), CD276 (12% identical), and 3 more.
Diseases named in the same sentence as BTNL2 in open-access papers:
BTNL2 is named in the same sentence as 67 diseases in open-access papers, as found by Europe PMC text mining. Sharing a sentence is not in itself a finding about the gene and the disease. The quoted sentences say what the papers report.
sarcoidosis (45 papers, 2006 to 2025). Sarcoidosis is a multisystemic disorder of unknown cause characterized by the formation of immune granulomas in involved organs. "For instance, one study detailed certain chromosome linkages to sarcoidosis, i.e., chromosome 5 in African Americans and chromosome 6 in German families, specifically the BTNL2 gene of chromosome 6 being associated with sarcoidosis." (PMID 40078389, 2025). "Genetic mutations in ANXA11 and BTNL2 appear to influence susceptibility and disease progression in sarcoidosis." (PMID 41306810, 2025). "BTNL2 inhibits T-cell proliferation, thereby linking BTNL2 polymorphisms with inflammatory/’autoimmune’ diseases such as sarcoidosis or myositis." (PMID 37407551, 2023). "BTNL2 has also been associated with atopic asthma in children in Korea, dust-mite-specific IgE response in a Japanese population, and sarcoidosis in a White German population." (PMID 37415598, 2023). "The BTNL2 mutation has been recently associated with inflammatory autoimmune diseases such as sarcoidosis and myositis." (PMID 34506591, 2021). "In fact, the BTNL2 polymorphism (rs2076530) has been registered in the dbSNP database as a risk factor for sarcoidosis." (PMID 34506591, 2021). "BTNL2 (Butyrophilin Like 2) (rs2076530) is a protein coding gene and has been linked to sarcoidosis." (PMID 33396862, 2020). "SNPs in a non-coding region of BTNL2, rs2076525 and rs2076524, were significantly associated with sarcoidosis (OR = 1.71)." (PMID 31126090, 2019). "Here, the novel variant in BTNL2 5’ region associated independently with distinct sarcoidosis phenotype (rs3135365 with NL) supporting the importance of the BTNL2 promoter region in sarcoidosis disease development." (PMID 28469621, 2017). "The increasing line of evidence suggests that BTNL2, a member of the immunoglobulin gene superfamily, is a key element for sarcoidosis predisposition." (PMID 28469621, 2017). "One of the two T1D proxy SNPs (rs9268480) inside the coding region of BTNL2 was 28 bp upstream from rs2076530, previously shown to cause splicing-related disruption of BTNL2 and an increased risk for sarcoidosis." (PMID 28081217, 2017). "Five SNPs were associated with the disease course of sarcoidosis (BTNL2 exonic SNP rs28362677, BTNL2 promoter SNP rs5007259, SNPs rs3135351 and rs3129843 between genes BTNL2 and HLA-DRA, and HLA-DRA downstream SNP rs3129877)." (PMID 28469621, 2017). "Our finding further establishes that polymorphisms in the HLA-DRA and BTNL2 have a role in sarcoidosis susceptibility." (PMID 28469621, 2017). "We therefore tested genetic variants known to be strongly associated with an increased risk of CD (NOD2, IRGM, IL23R, and ATG16L1), sarcoidosis (BTNL2), and atopy (FLG) for association with OFG." (PMID 27306066, 2016). "DNA samples from 201 patients (111 OFG only and 90 OFG+CD) were genotyped for variants known to be strongly associated with an increased risk of CD (NOD2, IRGM, IL23R, and ATG16L1), sarcoidosis (BTNL2), and atopy (FLG)." (PMID 27306066, 2016). "A recent meta-analysis has confirmed that BTNL2 rs2076530 polymorphism contributes to the risk of sarcoidosis." (PMID 27914482, 2016). "We genotyped 201 patients and 1023 healthy controls for risk variants in NOD2, IRGM, IL23R, ATG16L1 (CD), BTNL2 (sarcoidosis), and FLG (atopy)." (PMID 27306066, 2016). "In conclusion, this is the first meta-analysis concerning BTNL2 rs2076530 polymorphism and sarcoidosis susceptibility up to date." (PMID 25849037, 2015). "The significant increased A allele of BTNL2 rs2076530 observed in sarcoidosis group, implys the role of this truncating single nucleotide polymorphism in sarcoidosis susceptibility." (PMID 25849037, 2015). "This meta-analysis extended previous findings on the association between the BTNL2 rs2076530 polymorphism and sarcoidosis, by showing that the A allele of BTNL2 rs2076530 was associated with an increased risk of sarcoidosis susceptibility." (PMID 25849037, 2015).
sarcoidosis (continued). "We found that the A allele of BTNL2 rs2076530 was associated with an increased risk of sarcoidosis in allelic model (A vs. G, P<0.00001)." (PMID 25849037, 2015). "We provided convincing evidence on the contributory effect of BTNL2 rs2076530 polymorphism in the development of sarcoidosis." (PMID 25849037, 2015). "The aim of this study was to investigate the association of the BTNL2 rs2076530 polymorphism and sarcoidosis susceptibility by conducting a meta-analysis in ten case–control studies including 5817 subjects." (PMID 25849037, 2015). "Butyrophilin-like 2 (BTNL2) rs2076530 gene polymorphism has been implicated in susceptibility to sarcoidosis." (PMID 25849037, 2015). "This meta-analysis indicates that BTNL2 rs2076530 polymorphism contributes to the risk of sarcoidosis." (PMID 25849037, 2015). "Several studies have been undertaken to evaluate this potential relationship between BTNL2 rs2076530 polymorphism and sarcoidosis susceptibility." (PMID 25849037, 2015). "Among multiple potential factors contributing to sarcoidosis, one of them is the polymorphism of butyrophilin-like 2 (BTNL2) gene." (PMID 25849037, 2015). "These characters of our meta-analysis indicated a reliable and stable result about the association between BTNL2 rs2076530 polymorphism and sarcoidosis risk." (PMID 25849037, 2015). "In an effort to clarify the association of BTNL2 rs2076530 polymorphism and sarcoidosis susceptibility, we performed a meta-analysis on all the studies identified by systematic review of literatures." (PMID 25849037, 2015). "For the association of the BTNL2 rs2076530 polymorphism and sarcoidosis susceptibility among the overall populations, the observed significant result was not materially altered after sequentially excluding each study." (PMID 25849037, 2015). "Polymorphisms within butyrophilin-like 2 (BTNL2) gene - located in close proximity of the HLA complex on chromosome 6 - have been associated with sarcoidosis independently of HLA-DRB1 alleles." (PMID 23075428, 2012). "A follow-up study found that sarcoidosis is associated with a truncating splice site mutation in BTNL2." (PMID 18811966, 2008). "Both BTN1A1 and BTNL2 have been reported to exert immunomodulatory functions and foster immune evasion when expressed on cancer cells and BTNL2 has been associated with immunological disorders such as sarcoidosis." (PMID 39035010, 2024). "The expression of BTNL2 has been linked to sarcoidosis in the liver." (PMID 35686237, 2022). "For example, a family-based study among sarcoidosis-affected German families led to the discovery of a mutation in a putative immune regulatory gene, butyrophilin-like 2 (BTNL2), that may explain 23% of the attributable risk in that population." (PMID 29163767, 2017). "Here, we cannot exclude that the BTNL2-sarcoidosis association we observed is the consequence of gene proximity in the 6p21 area with a synergistic effect of some HLA class II haplotypes and the truncated form of BTNL2 on T-cell activation and proliferation process." (PMID 27914482, 2016). "Taken together these data demonstrate clearly that, with an OR = 2.0, the rs2076530 splicing variant of BTNL2 should be considered as a genetic risk factor for sarcoidosis but cannot be considered as a major gene explaining a Mendelian inheritance in the familial form of the disease." (PMID 27914482, 2016). "The sarcoidosis risk variant rs2076530 in BTNL2 was associated with all OFG (P = 0.013)." (PMID 27306066, 2016). "Finally, the fifth signal is rs2076530 (p=2.21E-08), which is a regulatory SNP in proximity to BTNL2 that has previously been associated with sarcoidosis and autoimmunity." (PMID 26880555, 2016). "BTNL2 gene in OMIM was labeled as a sarcoidosis disease susceptibility gene." (PMID 26253105, 2015).
sarcoidosis (continued). "Combined data indicated that BTNL2 rs2076530 polymorphism was associated with sarcoidosis susceptibility in allelic model (A vs. G, OR = 1.59, 95%CI: 1.47–1.72), dominant model (AA + AG vs. GG, OR = 2.10, 95%CI: 1.67–2.65), and recessive model (AA vs. AG + GG, OR = 1.93, 95%CI: 1.49–2.50)." (PMID 25849037, 2015). "However, this meta-analysis only assessed the association of BTNL2 rs2076530 polymorphism and sarcoidosis susceptibility." (PMID 25849037, 2015). "In addition, polymorphisms in the human gene encoding for BTNL2 have been linked to a growing number of inflammatory diseases, e.g. sarcoidosis, myositis and inflammatory bowel disease." (PMID 23829304, 2013). "The BTNL2-conferred sarcoidosis risk has been noted in both Caucasians and African-Americans." (PMID 18811966, 2008). "Furthermore, a recently described splice-site polymorphism of the BTNL2 gene has been reported to represent a HLA independent risk factor for another granulomatous disorder affecting the lung, namely sarcoidosis." (PMID 16526951, 2006). "Similarly, sarcoidosis has been shown to be associated with particular alleles in BTNL2, IL18, and IFNa, and SLC11A1." (PMID 16608528, 2006). "Both HLA-DRA (human leukocyte antigen class II histocompatibility antigen, DR alpha chain) and BTNL2 (butyrophilin-like 2, major histocompatibility complex class I associated) have previously been implicated in other inflammatory conditions such as multiple sclerosis and sarcoidosis." (PMID 38450615, 2024). "Some identified genes that may be associated with increased susceptibility to sarcoidosis are butyrophilin-like 2 gene (BTNL2), annexin A11 (ANXA11), and angiotensin-converting enzyme (ACE) variants; these associations, however, show high variability across populations." (PMID 39274446, 2024). "Genome-wide linkage and some studies have suggested that several genes may be associated with increased susceptibility to sarcoidosis, such as butyrophilin-like 2 gene (BTNL2), annexin A11 (ANXA11), and angiotensin-converting enzyme variants, although the associations vary across populations." (PMID 37108489, 2023). "Thus, the dysregulation of T-cell function from some BTNL2 mutations may explain its relationship to sarcoidosis." (PMID 31126090, 2019). "These three SNPs belong to the genes DGKB, BTNL2, and TGFBR3 that were indicated in previous genome wide association studies with CVD (DGKB), rheumatoid arthritis and sarcoidosis (BTNL2), and bone mass and osteoporosis (TGFBR3), respectively." (PMID 34201265, 2021). "In genome-wide association studies, these genes have been identified in connection with myocardial infarction (DGKB); immune function, rheumatoid arthritis, and sarcoidosis (BTNL2); and bone mass in different ethnic groups (TGFBR3)." (PMID 34201265, 2021). "Probably, the most investigated variant in the MHC class III, the splice-site SNP in BTNL2 (OMIM 606000) gene (rs2076530 G>A), has so far shown contradictory results with different sarcoidosis phenotypes and populations." (PMID 28469621, 2017). "To detect variants predisposing to sarcoidosis and to identify genetic differences between patient subgroups, we studied four genes in the MHC Class III region (LTA, TNF, AGER, BTNL2) and HLA-DRA with tag-SNPs and their relation to HLA-DRB1 alleles." (PMID 28469621, 2017). "As others, we suggest strongly that BTNL2 screening belongs to the panel of biomarkers in the diagnosis of sarcoidosis together with HLA class II haplotyping and further coming genes." (PMID 27914482, 2016). "Of the ten included studies, five articles provided genotype distributions of BTNL2 gene rs2076530 in sarcoidosis group (containing 1629 subjects) and control group (containing 1065 subjects)." (PMID 25849037, 2015). "We replicated associations for several previously reported sarcoidosis susceptibility risk loci in our AA collection including MHC Class II region genes (HLA-DRA, HLA-DRB5, HLA-DRB1, and HLA-DQA1), BTNL2, RAB23, and ANXA11." (PMID 22952805, 2012).
sarcoidosis (continued). "In a recent study on the granulomatous disorder sarcoidosis, a fine mapping approach using SNPs led to the definition of an HLA independent genetic factor, BTNL2." (PMID 16526951, 2006). "Other genes, including Butyrophilin-like-2 (which influences T-cell regulation), SLC11A1 (which encodes macrophage membrane protein) and Annexin A11 (which is involved in cell apoptosis), are all associated with different sarcoidosis phenotypes." (PMID 40002701, 2025). "Our eQTL/GWAS analysis also identified rs2393915 in EAs with complicated sarcoidosis associated to BTN3A2, BTN3A3 and BTN2A3P, MHC I-associated genes; other BTNL2 polymorphisms (rs2076530, rs206530), have been previously reported associated to sarcoidosis susceptibility." (PMID 38390497, 2023). "This interesting observation was highlighted by the fact the main BTNL-2 SNP related to sarcoidosis, rs2076530, induces the activation of a cryptic splice site located 4 bp upstream of the exon five-intron wild-type donor splice-site site and a premature a premature stop in the spliced mRNA." (PMID 32823753, 2020). "In conclusion, we found novel SNPs in BTNL2 and HLA-DRA regions associating with sarcoidosis." (PMID 28469621, 2017). "Six SNPs [rs9268528 (BTNL2 promoter), rs3135351, and rs3129843 (between genes HLA-DRA and BTNL2), rs9268644 and rs3129877 (HLA-DRA intronic), rs6937545 (downstream of HLA-DRA)] were associated with the disease course of sarcoidosis." (PMID 28469621, 2017). "We investigated BTNL2 gene in familial forms of sarcoidosis to assess the role of this gene as a major indicator of hereditary predisposition to the disease and find out whether it can be a useful genetic marker for clinical management and prognosis." (PMID 27914482, 2016). "After evaluating titles and abstracts, forty results were excluded for not relating to original study about association of BTNL2 rs2076530 polymorphism and sarcoidosis susceptibility." (PMID 25849037, 2015). "In particular, it is worthy to note that BTNL2 rs2076530 polymorphism was not strongly associated with sarcoidosis in African Americans in American GWAS." (PMID 25849037, 2015). "Third, we selected only five polymorphisms from TNF-α and TNF-β genes, and did not cover other sarcoidosis-susceptibility genes, such as annexin A11 gene and butyrophilin-like 2 gene." (PMID 24244632, 2013). "The previously reported peak SNP within BTNL2 (rs2076530) was not strongly associated with sarcoidosis in our AA datasets (PAA-meta = 0.024)." (PMID 22952805, 2012). "An association of sarcoidosis with rs2076530, a coding SNP on exon 5 of the BTNL2 gene has been reported, but the SNP was not in LD with rs10947262 (D' = 0.11, r2 = 0)." (PMID 20305777, 2010). "Variation at BTNL2 (6p21.32) has been associated with Grave's disease, multiple sclerosis, and sarcoidosis, apparently independent of the neighboring HLA class DR genes." (PMID 19936222, 2009). "For instance rs2076530 (A/G), a single nucleotide polymorphism (SNP) in BTNL2 (butyrophilin-like 2, a MHC class II associated gene), has been shown to be strongly associated with several autoimmune diseases such as MS, RA, T1D, sarcoidosis and systemic lupus erythematosus (SLE)." (PMID 20041220, 2009). "The odds ratio (OR) associated with rs2076530 was estimated at 1.8 to 2.0 in several studies, but we demonstrated in a French cohort that this BTNL-2 variant could not explain the autosomal dominant predisposition to sarcoidosis in affected families." (PMID 32823753, 2020). "In addition, several genetic variants within or near non-HLA genes were also significantly associated with sarcoidosis: BTNL2, PTGS2/COX2, and PACERR (PTGS2 Antisense NFKB1 Complex-Mediated Expression Regulator RNA)." (PMID 31126090, 2019). "However, we have previously shown that this variant did not discriminate the sporadic and familial forms of the disease, thus suggesting BTNL2 is not a major gene predisposing to sarcoidosis." (PMID 29510755, 2018).
sarcoidosis (continued). "However, BTNL2 polymorphism was shown linked to sarcoidosis regardless of ethnicity in Caucasian, Afro-American, and Japanese patients." (PMID 27914482, 2016). "Here, the BTNL2 rs2076530 splice variant could not distinguish sporadic from familial forms and we still have to understand pathways through which the truncated form of BTNL2 may be involved in the pathogenesis of sarcoidosis." (PMID 27914482, 2016). "The French national program of the GSF network (Group Sarcoidosis France) for ten years has focused on the familial forms of sarcoidosis (the SARCFAM project) and initially excludes the BTNL2 gene as a major predisposing factor to the disease." (PMID 32823753, 2020). "BTNL2 is thought to act as a negative co-stimulatory molecule, thus non-functional BTNL2 could theoretically result in an exaggerated T lymphocyte activation, compatible with the proposed pathophysiology of sarcoidosis." (PMID 23075428, 2012). "Several other non-HLA genes have been associated with sarcoidosis, such as prostaglandin G/H synthase/cyclooxygenase (PTGS2/COX2), neurogenic locus notch homolog 4 (NOTCH4), nucleotide-binding oligomerization domain-containing protein 2 (NOD2), and Butyrophilin-like 2 (BTNL2)." (PMID 31126090, 2019).